RNU6-995P (RNA, U6 small nuclear 995, pseudogene)
Gene: Small nuclear RNA gene on chromosome X (80,936,434 to 80,936,540, forward strand). Ensembl gene ENSG00000212546.
Homologues: Orthologues: chimpanzee U6 (98% identical), macaque U6 (85% identical), pig U6 (76% identical), pig U6 (70% identical). Paralogues in human: RNU6-1083P (84% identical), RNU6-348P (84% identical), RNU6-1124P (83% identical), RNU6-1310P (83% identical), RNU6-19P (83% identical), RNU6-338P (83% identical), RNU6-1175P (82% identical), RNU6-12P (82% identical), RNU6-13P (82% identical), RNU6-142P (82% identical), RNU6-24P (82% identical), RNU6-25P (82% identical), and 1285 more.